EGFR (epidermal growth factor receptor)
Diseases named in the same sentence as EGFR in open-access papers (continued):
Sharing a sentence is not in itself a finding about the gene and the disease.
non-small cell lung carcinoma (continued). "Erlotinib is an agent of oral epidermal growth factor receptor (EGFR) tyrosine kinase inhibitors which are used for non-small cell lung cancer." (PMID 22901999, 2012). "Epidermal growth factor receptor (EGFR) tyrosine kinase inhibitors (TKIs) such as gefitinib and erlotinib show promising therapeutic effects in patients with advanced non-small cell lung cancer (NSCLC)." (PMID 22429575, 2012). "EGFR is a target that is overexpressed in high levels on cancer cell surfaces in general, and particularly on non-small cell lung cancer (NSCLC) cells." (PMID 22685658, 2012). "Frequencies of EGFR and KRAS mutations in non-small cell lung cancer (NSCLC) have predominantly been determined in East Asian and North American populations, showing large differences between these populations." (PMID 22528563, 2012). "Specifically, frequent abnormal amplification or activation of EGFR has been observed in non-small cell lung cancer (NSCLC)." (PMID 22433462, 2012). "Several methods for the evaluation of EGFR-status in non-small cell lung cancer have been described." (PMID 23088930, 2012). "One of the most important pathways in non-small cell lung cancer (NSCLC) is the epidermal growth factor receptor (EGFR) pathway." (PMID 23691449, 2012). "This study aimed to detect RBM5 expression in non-small cell lung cancer (NSCLC) and to associate RBM5 expression with clinicopathological data from NSCLC patients and EGFR and KRAS expression to better understand the potential role of RBM5 in NSCLC." (PMID 22537942, 2012). "The epidermal growth factor receptor (EGFR) is a validated therapeutic target in non-small cell lung cancer (NSCLC)." (PMID 22436374, 2012). "During the past 10 years, epidermal growth factor receptor (EGFR) tyrosine kinase inhibitors (TKIs) have become the most promising treatment for advanced non-small cell lung cancer (NSCLC)." (PMID 23050865, 2012). "Elevated levels of EGFR expression and activity are frequently correlated with the radiotherapy resistance of tumors, including that of non-small cell lung cancer (NSCLC)." (PMID 22681918, 2012). "Adenocarcinoma with an epidermal growth factor receptor gene mutation (exon 19 deletion L747-E749; A750P) was detected in a transbronchial biopsy specimen; the patient was diagnosed with stage IV (T2N2M1) non-small cell lung cancer." (PMID 23079208, 2012). "Immunohistochemical staining with deletion specific 6B6 monoclonal antibody in Non-Small Cell Lung Cancers carrying different deletions at exon 19 of the EGFR gene detected by Next Generation Sequencing." (PMID 22848739, 2012). "EGFR overexpression in non-small cell lung cancer (NSCLC) is variable ranging from 19% to 89% and its prognostic value remains controversial." (PMID 21385353, 2011). "The poor response to the EGFR inhibitor gefitinib in patients with non-small cell lung carcinoma was correlated with an increase in serum levels of AR and TGF-α." (PMID 24212818, 2011). "Epidermal growth factor receptor (EGFR) is a novel target for therapy in subsets of non-small cell lung cancer, especially adenocarcinoma." (PMID 21858063, 2011). "Gefitinib (ZD1839, Iressa; AstraZeneca) and erlotinib (Tarceva, OSI-774; OSI Pharmaceuticals) are orally active epidermal growth factor receptor tyrosine kinase inhibitors (EGFR-TKIs) used for the treatment of non-small cell lung cancer (NSCLC) patients." (PMID 21791074, 2011). "The aim of this study is to investigate the expression and clinical relevance of c-Cbl, Cbl-b and EGFR in non-small cell lung cancer (NSCLC)." (PMID 21645455, 2011). "A critical role for oncogenic mutations is illustrated by the example of epidermal growth factor receptor (EGFR/ERBB1) in Non Small Cell Lung Cancer (NSCLC), where only a subset of patients respond to the EGFR inhibitor gefitinib." (PMID 21379385, 2011). "Epidermal growth factor receptor (EGFR) tyrosine kinase inhibition is an active strategy in non-small cell lung cancer (NSCLC)." (PMID 22108465, 2011).
non-small cell lung carcinoma (continued). "Gefitinib was the first epidermal growth factor receptor tyrosine kinase inhibitor (EGFR-TKI) to become available for the treatment of non-small cell lung cancer (NSCLC)." (PMID 21194487, 2011). "The heterodimerization of EGFR with IGF1R in response to treatment with the EGFR TK inhibitor erlotinib has been described in non-small cell lung carcinoma (NSCLC) cells and is related to the subsequent development of drug resistance." (PMID 24212818, 2011). "A high incidence of interstitial lung disease (ILD) has been reported in patients with advanced non-small cell lung cancer (NSCLC) treated with epidermal growth factor receptor-tyrosine kinase inhibitors (EGFR-TKIs), particularly in Japanese populations." (PMID 21791074, 2011). "Gefitinib is FDA approved for the treatment of advanced non-small cell lung cancer and attaches to the ATP-binding site of the EGFR." (PMID 22088142, 2011). "Gefitinib, a tyrosine kinase inhibitor of the epidermal growth factor receptor (EGFR), is a new molecular target agent for the treatment of patients with advanced non-small cell lung cancer who fail to respond to chemotherapy." (PMID 22096546, 2011). "Autophagy inhibition thus represents a promising approach to improve the efficacy of EGFR-TKIs in the treatment of patients with advanced non-small-cell lung cancer." (PMID 21655094, 2011). "Gefitinib (Iressa) is an inhibitor of the epidermal growth factor receptor (EGFR) that has shown promising activity in the treatment of patients with non-small cell lung cancer (NSCLC)." (PMID 22022498, 2011). "A bibliographic search of the Medline database was conducted for papers published from 1 January 2000 to 1 July 2010, with the keywords ‘non-small-cell lung cancer’, ‘epidermal growth factor receptor’, ‘erlotinib’ ‘gefitinib’ and ‘cetuximab’." (PMID 21654681, 2011). "Treatment of EGFR-mutant non-small cell lung cancer patients with the tyrosine kinase inhibitors erlotinib or gefitinib results in high response rates and prolonged progression-free survival." (PMID 21573178, 2011). "Epidermal growth factor receptor tyrosine kinase inhibitors (EGFR-TKI) have been widely used for the treatment of non-small cell lung cancer (NSCLC)." (PMID 21414214, 2011). "EGFR inhibition by anti-EGFR monoclonal antibodies (MAbs) or tyrosine kinase inhibitors (TKIs) represents a particularly successful molecular targeted therapy for tumors such as Non-Small Cell Lung Cancer and Colorectal Cancer." (PMID 22185378, 2011). "EGFR is often overexpressed in non-small cell lung cancer (NSCLC) and a variety of common solid tumors." (PMID 21943352, 2011). "In many human cancers, such as colorectal cancer and non-small-cell lung cancer, EGFR overexpression is correlated with cellular proliferation, angiogenesis and tumor growth, leading to disease progression involving invasion and metastasis." (PMID 21966417, 2011). "The epidermal growth factor receptor (EGFR) monoclonal antibody cetuximab has been used widely in non-small cell lung cancer patients." (PMID 20704815, 2010). "One of the mutations (L858R) was previously identified in non-small cell lung cancer (NSCLC) patients and this mutation was found to increase sensitivity to EGFR inhibitor, Erlotinib." (PMID 20942962, 2010). "Based on the poor overall outcome and significant toxicity of upfront chemotherapy in advanced non-small cell lung cancer, EGFR TKI therapy as front-line treatment has significant appeal for the appropriate patient." (PMID 21165163, 2010). "Recently, EGFR-targeted therapy has proven effective in treating non-small cell lung cancer (NSCLC)." (PMID 20637128, 2010). "With the availability of effective anti-EGFR therapies for various solid malignancies, such as non-cell small lung cancer, colorectal cancer and squamous cell carcinoma of the head and neck, the knowledge of EGFR and K-RAS status becomes clinically important." (PMID 20459770, 2010).
non-small cell lung carcinoma (continued). "EGFR TKIs have comparable clinical efficiency with the best supportive care or standard chemotherapy as second-line or third-line therapy for advanced non-small-cell lung cancer." (PMID 20433767, 2010). "EGFR overexpression in non small cell lung cancer (NSCLC) and colorectal cancer (CRC) is a frequent event related to a poor outcome." (PMID 20843314, 2010). "Epidermal growth factor receptor (EGFR) is the most important therapeutic target in non-small cell lung cancer (NSCLC)." (PMID 20840812, 2010). "EGFR-scores for the analyzed primary Non-small cell Lung cancer and the corresponding lymph node metastases (n = 47)." (PMID 20096104, 2010). "MCL-1 was also found to be modulated by PI3K/TOR signaling in the setting of mutant epidermal growth factor receptor (EGFR) driven non-small cell lung cancers." (PMID 20657741, 2010). "Cetuximab, an antibody targeting the epidermal growth factor receptor (EGFR), increases survival in patients with advanced EGFR-positive non-small cell lung cancer when administrated in combination with chemotherapy." (PMID 20529262, 2010). "The aim of this study is to investigate the expressions and their significances of vascular endothelial growth factor-C (VEGF-C) mRNA and epidermal growth factor receptor (EGFR) mRNA in non-small cell lung cancer (NSCLC) tissues and lymph node tissues." (PMID 21159248, 2010). "In non-small cell lung cancers (NSCLC), activating EGFR mutations are found in 10–15% of Caucasian and 30–40% Asian patients." (PMID 21049007, 2010). "Over the last few years, we have seen a revolution in the understanding of the appropriate use of EGFR-targeted therapy in non-small cell lung cancer." (PMID 21165163, 2010). "In non-small cell lung cancer, the relationship between KRAS mutation and response to EGFR inhibitors is less clear." (PMID 20591134, 2010). "The EGFR antagonists are included in treatment protocols of advanced stages of non-small cell carcinoma of the lung, colorectal cancer and head and neck squamous cell carcinoma." (PMID 20664595, 2010). "The EGFR (exon 19) 15 bp or 18 bp microdeletions are commonly found in 5–20% of patients with non-small cell lung cancers." (PMID 19789704, 2009). "Epidermal growth factor receptor (EGFR) deregulation has been observed in multiple tumor types including non-small cell lung cancers (NSCLCs)." (PMID 19238210, 2009). "There are two classes of EGFR antagonists that are used in clinical practice for non-small cell lung cancer at this time: anti-EGFR monoclonal antibody (cetuximab), and small-molecule EGFR tyrosine kinase inhibitors (TKIs) (gefitinib and erlotinib)." (PMID 19159467, 2009). "There is a need for predictive biomarkers that identify non-small-cell lung cancer (NSCLC) patients most likely to respond to epidermal growth factor receptor (EGFR) tyrosine kinase inhibitor (TKI) treatment." (PMID 19861557, 2009). "The common 15 bp or 18 bp deletions in the epidermal growth factor receptor (EGFR) gene, commonly found in 5–20% of patients with non-small cell lung cancers, were chosen as models to explore the analytical sensitivity and analytical selectivity of MAP." (PMID 19789704, 2009). "At this time, two targeted agents are approved by the FDA in advanced non-small cell lung cancer (NSCLC): the epidermal growth factor receptor (EGFR) tyrosine kinase inhibitor (TKI) erlotinib, and the anitangiogenic bevacizumab." (PMID 19159467, 2009). "We next show some example toxicity data for the targeted drug erlotinib, which is an EGFR inhibitor used in treating solid malignancies such as non-small cell lung cancer." (PMID 19893626, 2009). "For example, missense mutations or small in-frame deletions within the kinase domain, which render EGFR constitutively active, are observed in a subset of patients with non-small cell lung cancer (NSCLC)." (PMID 19948031, 2009).
non-small cell lung carcinoma (continued). "It seems not to be disease specific as it occurs in patients treated with EGFR targeted therapies for colorectal cancer, pancreatic cancer, head & neck cancer and non small cell lung cancer." (PMID 19584908, 2009). "The identification of patients that are likely to benefit from EGFR TKI therapy is a priority for patients with advanced non-small cell lung cancer." (PMID 19765296, 2009). "EGFR kinase domain mutants found in non-small cell lung cancer (NSCLC) are constitutively active, a trait critical for cell transformation through activation of downstream pathways." (PMID 19948031, 2009). "Inhibition of the epidermal growth factor receptor (EGFR) has shown clinical success in patients with advanced non-small cell lung cancer (NSCLC)." (PMID 19079597, 2008). "The FDA has approved two EGFR-specifc TKIs, Iressa (Gefitinib) [December 2004] and Tarceva (Erlotinib) [November 2004], for the treatment of non-small cell lung carcinoma." (PMID 21892266, 2008). "Much attention has been drawn to the oncogenic effect of EGFR and most of all to success of EGFR target therapies, which are well established for non small cell lung carcinomas." (PMID 18199332, 2008). "Many synthetic compounds that inhibit phosphorylated STAT3 and EGFR tyrosine kinase activity have been shown to be effective in preclinical studies and in clinical trials of advance stages of non-small cell lung cancer, breast, and ovarian cancer." (PMID 18302761, 2008). "Amplification of gene locus is acommon mechanism of regulation of EGFR in other tumours such as head and necksquamous cell carcinomas, non-small-cell lung carcinomas, and colorectal carcinomas." (PMID 18769552, 2008). "PTEN has been found to confer resistance to EGFR-inhibitors in glioblastoma, prostate, breast and non-small-cell lung cancer, and this resistance appears to be due to its function as a negative regulator of the phosphatidylinositol 3' kinase (PI3K) complex." (PMID 18700047, 2008). "Erlotinib is a Human Epidermal Growth Factor Receptor Type 1/tyrosine kinase (EGFR) inhibitor which is used for non-small-cell lung cancer treatment." (PMID 17683587, 2007). "Subsets of patients with non-small cell lung cancer respond remarkably well to small molecule tyrosine kinase inhibitors (TKI) specific for epidermal growth factor receptor (EGFR) such as gefitinib or erlotinib." (PMID 17325698, 2007). "Second, a linear relationship was also demonstrated between Yellow intensity and visual scoring for NovaRed-labeled epidermal growth factor receptor in 256 non-small cell lung cancer biopsies." (PMID 17326824, 2007). "Cytology specimens obtained by transbronchial abrasion were successfully used for analysis of the EGFR gene status in 50 of 52 (96.2%) patients diagnosed with class V non-small-cell carcinoma." (PMID 17047654, 2006). "Increased focus surrounds identifying patients with advanced non-small cell lung cancer (NSCLC) who will benefit from treatment with epidermal growth factor receptor (EGFR) tyrosine kinase inhibitors (TKI)." (PMID 17096850, 2006). "It has been shown in clinical studies that EGFR is overexpressed in 40–80% of non-small-cell lung carcinomas (NSCLCs), and in preneoplastic lesions." (PMID 16052218, 2005). "EGFR is frequently overexpressed in non-small-cell lung cancer (NSCLC), especially in squamous cell carcinoma, and its expression is related to the cancer's proliferation." (PMID 15696203, 2005). "EGFR-TKIs are generally well tolerated and can sometimes produce impressive tumour regression in patients with advanced non-small-cell lung cancer." (PMID 15150574, 2004). "Epidermal growth factor receptors (EGFr) were measured using a radioligand binding assay, in membrane preparations from 51 human non-small cell lung cancers and in normal tissue of the same patients." (PMID 1654986, 1991).
non-small cell lung carcinoma (continued). "A total of 152 non-small cell lung cancers (NSCLC) were studied retrospectively to determine the relationship between epidermal growth factor receptor (EGF-R) status and the histological type, tumour size, nodal status and prognosis." (PMID 2544220, 1989). "Similarly, the EGFR/MAPK/LOX axis has been shown to promote the metastatic spread of non-small cell lung cancer." (PMID 41399365, 2026). "Inactivating vascular endothelial growth factor receptor (VEGFR) may improve the efficacy of epidermal growth factor receptor (EGFR) tyrosine kinase inhibitors (TKIs) in EGFR-mutant non-small cell lung cancer (NSCLC)." (PMID 41629265, 2026). "Some patients with EGFR-mutant non-small cell lung cancer may exhibit resistance to EGFR-TKI treatment, which can be primary or secondary." (PMID 40004680, 2025). "Drawing on experiences from treating EGFR gene mutations, the most common oncogenic drivers in non-small cell lung cancer, EGFR-TKI targeted therapy may be applicable to patients with AF carrying EGFR mutations." (PMID 40727479, 2025). "Similarly, in patients suffering from EGFR/ALK wild-type metastatic non-small-cell lung carcinoma, durvalumab and tremelimumab together with chemotherapy showed better OS and PFS benefit relative to chemotherapy in the phase III POSEIDON trial (NCT03164616)." (PMID 40918459, 2025). "Recent evidence regarding non-small cell lung cancer suggests that co-alterations in EGFR and CDKN2A may enhance oncogenicity and reshape the immune microenvironment." (PMID 41463200, 2025). "Additionally, miR30b also acted as an apoptosis inhibitor through the targeting of caspase 3 in a glioblastoma model and EGFR in a non-small-cell lung cancer model, leading to apoptosis resistance and drug resistance." (PMID 40732337, 2025). "Notably, studies have explored the synergistic effects of afatinib, an EGFR inhibitor, on the radiosensitivity in non-small-cell lung cancer patients." (PMID 40564086, 2025). "Clinically, EGFR tyrosine kinase inhibitor (EGFR-TKI) therapies have been shown to be effective in late-stage (advanced) EGFR-mutant non-small cell lung cancer (NSCLC) patients, and the surgical removal of tumor is still the standard option for early-stage NSCLC patients." (PMID 40723259, 2025). "In addition, CIB2 holds potential as a therapeutic target for overcoming epidermal growth factor receptor-tyrosine kinase inhibitor (EGFR-TKI) resistance in non-small-cell lung cancer (NSCLC)." (PMID 40076845, 2025). "The advent of molecularly targeted small molecule inhibitors, exemplified by epidermal growth factor receptor (EGFR)-targeted tyrosine kinase inhibitors (TKIs), has notably improved treatment outcomes for patients diagnosed with non-small cell lung cancer (NSCLC)." (PMID 41514577, 2025). "Conversely, KRAS mutations are present in only approximately 30% of lung adenocarcinomas, while EGFR mutations occur in 10-15% of non-Asian and up to 50% of Asian patients with non-small cell lung cancer (NSCLC)." (PMID 40656425, 2025). "Currently, the molecular characteristics of non-small cell lung cancer (NSCLC) form the basis for clinical diagnosis and treatment of lesions (e.g., EGFR, KRAS), and the phenotypic associations between molecular subtypes and imaging semantic features have been widely studied." (PMID 40356757, 2025). "Also, we introduced 1,2,3-triazole groups with different substituents to obtain icotinib derivatives, among which compound a12 showed effective antitumor activity in non-small-cell lung cancers cells as a potent inhibitor for EGFR with IC50 value of 1.49 μM." (PMID 39926646, 2025). "There are approximately 10% to 15% of patients with non-small cell lung cancer (NSCLC) harboring MET amplification as a secondary driver of acquired resistance to targeted therapy including EGFR-TKIs or Anaplastic Lymphoma Kinase-Tyrosine Kinase Inhibitors (ALK-TKIs)." (PMID 40365349, 2025).